IRS1 (insulin receptor substrate 1)
Description:
Signaling adapter protein that participates in the signal transduction from two prominent receptor tyrosine kinases, insulin receptor/INSR and insulin-like growth factor I receptor/IGF1R. Plays therefore an important role in development, growth, glucose homeostasis as well as lipid metabolism. Upon phosphorylation by the insulin receptor, functions as a signaling scaffold that propagates insulin action through binding to SH2 domain-containing proteins including the p85 regulatory subunit of PI3K, NCK1, NCK2, GRB2 or SHP2. Recruitment of GRB2 leads to the activation of the guanine nucleotide exchange factor SOS1 which in turn triggers the Ras/Raf/MEK/MAPK signaling cascade (By similarity). Activation of the PI3K/AKT pathway is responsible for most of insulin metabolic effects in the cell, and the Ras/Raf/MEK/MAPK is involved in the regulation of gene expression and in cooperation with the PI3K pathway regulates cell growth and differentiation. Acts a positive regulator of the Wnt/beta-catenin signaling pathway through suppression of DVL2 autophagy-mediated degradation leading to cell proliferation.
Synonyms: HIRS-1
Tractability: Small molecule: a structure with a bound ligand is known; a high-quality ligand is known; it has a binding pocket of medium quality. Antibody: its Gene Ontology location is reachable by antibodies, with high confidence; the Human Protein Atlas places it where antibodies can reach. PROTAC: UniProt records ubiquitination sites on it; ubiquitination databases record sites on it; a small molecule that binds it is known.
Safety:
Unwanted effects reported when the protein is acted on. In parentheses: how it was acted on, where the effect was seen, and who reports it.
neutropenia (source: ClinPGx)
Gene: Protein-coding gene on chromosome 2 (226,731,312 to 226,799,820, reverse strand). Ensembl gene ENSG00000169047.
Subcellular location: Cytoplasm; Nucleus
Subcellular location (Human Protein Atlas): Cytosol; Nucleoplasm; Plasma membrane; Vesicles
Pathways (Reactome):
Signal Transduction: Activated NTRK3 signals through PI3K; IRS activation; IRS-mediated signalling; IRS-related events triggered by IGF1R; PI3K Cascade; PI3K/AKT activation; PI5P, PP2A and IER3 Regulate PI3K/AKT Signaling; PIP3 activates AKT signaling; RAF/MAP kinase cascade; SOS-mediated signalling; Signal attenuation; Signaling by ALK; Signaling by LTK; Signaling by Leptin
Disease: Constitutive Signaling by Aberrant PI3K in Cancer; Signaling by ALK fusions and activated point mutants
Immune System: Growth hormone receptor signaling; Interleukin-7 signaling
Gene Ontology:
Molecular function: insulin receptor binding; insulin-like growth factor receptor binding; phosphatidylinositol 3-kinase binding; phosphotyrosine residue binding; protein binding; signaling adaptor activity; signaling receptor complex adaptor activity; protein kinase C binding; SH2 domain binding; transmembrane receptor protein tyrosine kinase adaptor activity; signaling receptor binding
Biological process: cellular response to insulin stimulus; cytokine-mediated signaling pathway; insulin receptor signaling pathway; insulin-like growth factor receptor signaling pathway; negative regulation of insulin secretion; phosphatidylinositol 3-kinase/protein kinase B signal transduction; positive regulation of D-glucose import; positive regulation of fatty acid beta-oxidation; positive regulation of glucose metabolic process; positive regulation of glycogen biosynthetic process; positive regulation of insulin receptor signaling pathway; response to insulin; cellular response to fatty acid; glucose homeostasis; negative regulation of insulin receptor signaling pathway; positive regulation of cell population proliferation; positive regulation of phosphatidylinositol 3-kinase/protein kinase B signal transduction; signal transduction; positive regulation of signal transduction
Cellular component: caveola; cytoplasm; nucleus; cytosol; insulin receptor complex; intracellular membrane-bounded organelle; plasma membrane
Genetic constraint (gnomAD): Loss-of-function variants: 34 observed, 67.13 expected, observed/expected ratio (o/e) 0.51, 90% interval 0.38 to 0.67. The upper end of that interval is the gene's LOEUF score, 0.67, which puts it in group 2 of 6, group 1 being the genes least tolerant of losing a copy. Missense variants: 1,641 observed, 1,776.2 expected, observed/expected ratio (o/e) 0.92, 90% interval 0.89 to 0.96. Synonymous variants: 699 observed, 710.45 expected, observed/expected ratio (o/e) 0.98, 90% interval 0.92 to 1.05.
Homologues: Orthologues: chimpanzee IRS1 (99% identical), macaque IRS1 (98% identical), pig IRS1 (92% identical), guinea pig IRS1 (92% identical), rabbit IRS1 (91% identical), rat Irs1 (90% identical), mouse Irs1 (89% identical), dog IRS1 (88% identical), tropical clawed frog irs1 (58% identical), zebrafish irs1 (56% identical), Drosophila melanogaster chico (19% identical). Paralogues in human: IRS2 (39% identical), IRS4 (25% identical).
Diseases named in the same sentence as IRS1 in open-access papers:
IRS1 is named in the same sentence as 263 diseases in open-access papers, as found by Europe PMC text mining. Sharing a sentence is not in itself a finding about the gene and the disease. The quoted sentences say what the papers report.
Insulin resistance (1,666 papers, 2004 to 2026). Increased resistance towards insulin, that is, diminished effectiveness of insulin in reducing blood glucose levels. "Gain- and loss-of-function studies indicate that insulin resistance or hyperglycemia-induced downregulation of IRS1 elevates KLF4 expression, a transcriptional repressor of the smooth muscle contractile phenotype." (PMID 40940776, 2025). "Our study demonstrates that the significantly changed expression of RAP1A, SESTRIN3, and IRS1 in PA-mTORC1-Akt pathway causes insulin resistance in T2DM macaques." (PMID 40878918, 2025). "Liver specific ablation of Mig-6 also causes hyperglycemia and insulin resistance in mice by increasing phosphorylation of insulin receptor substrate 1 (IRS-1) at serine 307 via EGFR-dependent manner." (PMID 39937764, 2025). "Expression of hepatic GCK is maintained through regulation by IRS-1 in hyperinsulinemia as insulin resistance develops and decreased suppression by IRS-2-linked FoxO1 signaling." (PMID 41196673, 2025). "In Alzheimer’s patients, insulin resistance in the brain, particularly in the hippocampus, characterized by elevated insulin receptor substrate 1 (IRS-1) serine phosphorylation, is linked to disrupted insulin signaling and reduced PI3K/Akt activity." (PMID 40137277, 2025). "TNF-α activates JNK, which is a kinase that causes insulin resistance via serine phosphorylation of IRS-1." (PMID 40274715, 2025). "By contrast, in vitiligo cells the mechanism appears inverse: the enhanced import of glucose due to mitochondrial inefficiency provokes chronic mTOR-S6 signal amplification and IRS1 phosphorylation feedback, causing insulin resistance." (PMID 40277891, 2025). "Numerous genetic markers associated with insulin resistance and cardiovascular disease have been identified, including variants in the IRS1, CHI3L1, and CD36 genes." (PMID 40564010, 2025). "In neurons of insulin-resistant mice, 48 h long hyperinsulinemia triggered deficient Tyr608 phosphorylation of IRS-1 and Thr308/Ser473 phosphorylation of Akt." (PMID 40430434, 2025). "This disruption causes insulin resistance by decreasing the tyrosine kinase activity of the IR and increasing the serine phosphorylation of Insulin Receptor Substrate 1 (IRS-1)." (PMID 40724491, 2025). "One of the critical mechanisms underlying insulin resistance is the impairment of insulin signaling via IRS-1." (PMID 39796627, 2025). "The typical manifestation involves insulin resistance, which is the main driving factor of atherosclerotic metabolic disorder caused by the imbalance of the IRS-1/PI3K/Akt pathway." (PMID 40718102, 2025). "The IRS1/PI3K/AKT pathway is a major signaling pathway associated with insulin resistance, mediating insulin-stimulated glucose uptake and utilization." (PMID 40565724, 2025). "The genetic polymorphism of IRS-1 leads to reduced IRS-1 expression, resulting in an increased visceral fat-to-subcutaneous fat ratio, insulin resistance, hyperlipemia, and decreased adiponectin levels." (PMID 40001466, 2025). "For example, the IRS1 (insulin receptor substrate 1) gene was reported to be associated with insulin resistance, T2D, and PCOS." (PMID 39859066, 2025). "TNF-α directly causes insulin resistance in skeletal muscle and adipose tissue by inhibiting the tyrosine phosphorylation of insulin receptor substrate 1 (IRS-1) and activating the IKK and JNK pathways." (PMID 40661082, 2025). "Specific haplotypes upstream of the insulin receptor substrate 1 (IRS1) gene are linked to insulin resistance, type 2 diabetes, and atherosclerosis." (PMID 40564010, 2025). "Insulin receptor substrate‐1 (IRS‐1) is a critical molecule in the insulin signaling pathway, and phosphorylation at its Ser307 site is closely linked to insulin resistance." (PMID 41394960, 2025). "The SGLT2i empagliflozin and DPP4i sitagliptin restore insulin sensitivity in HFD/STZ mice by decreasing IRS1 phosphorylation at Tyr632, associated with insulin resistance, and boosting AKT phosphorylation." (PMID 41146261, 2025).
Insulin resistance (continued). "In hepatocytes, a rise in IL-6 bears a close association with the onset of insulin resistance, typically via the downregulation of IRS-1 tyrosine phosphorylation and SOCS-3 expressional upsurge." (PMID 40427505, 2025). "This study revealed a strong association between the IRS1 gene and its surrounding genetic variants and T2DM, insulin resistance, and hyperinsulinemia, emphasizing the central role of IRS1 in the pathogenesis of T2DM." (PMID 40747301, 2025). "Reduced IRS function is linked to insulin resistance, and IRS1 is a critical regulator of VSMC differentiation." (PMID 40940776, 2025). "Analogously, the insulin receptor substrate-1 has been implicated in regulating insulin resistance via proteasomal degradation mediated by KLHL9/KLHL13/CUL339." (PMID 38834545, 2024). "The first mechanism is supported by the report that anti-TNFα treatment ameliorates insulin sensitivity and also by the findings that TNFα-activated JNK directly phosphorylates IRS1/2, causing insulin resistance." (PMID 38397480, 2024). "A recent Pakistani population study demonstrated a correlation between the Gly972Arg variant of IRS-1 and insulin resistance in T2DM." (PMID 38504356, 2024). "We observed an upregulation in the Ser307 phosphorylation of IRS1, a crucial substrate protein marker associated with insulin resistance, within these liver cells." (PMID 38441531, 2024). "Nilotinib, on a genetic level, causes insulin resistance modulated by genes such as IRS1 which can accelerate the decomposition of adipose tissue and increase the flow of free fatty acids into the liver." (PMID 39634983, 2024). "Significantly, we established a role for mTORC1/S6K1/IRS-1 signalling axis in the insulin resistance caused by KIC." (PMID 39464407, 2024). "Specifically, the brain insulin resistance phenomenon is associated with reduced levels of IR protein and increased levels of inhibitory phosphorylation of IRS1, which are responsible for the uncoupling between IR and IRS1." (PMID 39768255, 2024). "Serine/threonine residue phosphorylation of insulin receptor substrates (IRS1 Ser307) instead of tyrosine phosphorylation (Tyr612) causes insulin resistance." (PMID 39795155, 2024). "Catecholamines (ChAs), such as epinephrine and norepinephrine, can cause insulin resistance by suppressing the activity of insulin receptor substrate (IRS)-1." (PMID 39682557, 2024). "In the metabolically active organs, IL-6-mediated STAT3 activation destabilizes insulin receptor substrate 1 (IRS1) protein, causing insulin resistance." (PMID 38474057, 2024). "These receptors are associated with IRS1 and their function changes during metabolic diseases such as insulin resistance." (PMID 38961093, 2024). "TNF-α causes insulin resistance by stimulating serine phosphorylation of insulin receptor substrate-1(IRS-1) and interfering with the functions of β cells." (PMID 37346347, 2023). "In male mice, heart insulin resistance caused by cardiac IRS1 and IRS2 ablation induces heart failure and gradually leads to death, which is rescued by cardiac FoxO1 deletion." (PMID 37960324, 2023). "The G972R IRS1 polymorphism has been linked to a 50% reduction in insulin sensitivity, suggesting that the GG genotype would reduce insulin resistance and the risk of CRC." (PMID 37284192, 2023). "Consumption of LPLM141 exhibited a significant amelioration in insulin resistance, which were mechanistically caused by downregulation of the serum leptin level and upregulation of hepatic IRS-1 and p-Akt protein expressions, in HFD treated rats." (PMID 37114144, 2023). "It has also been suggested that RNA fragments of SARS-CoV-2 can activate PRK, which generates phosphorylation of insulin receptor substrate 1 (IRS-1) serine causing insulin resistance." (PMID 37515018, 2023).
Insulin resistance (continued). "One of the key mechanisms underlying vascular insulin resistance is impaired signaling of the insulin receptor substrate 1 (IRS-1) pathway, which is a critical mediator of insulin signaling in the blood vessels." (PMID 37610001, 2023). "Several studies have linked insulin resistance and elevated insulin concentrations (outside of the normal range) to the IRS1 gene, which plays a vital role in insulin signaling." (PMID 38026570, 2023). "The insulin receptor substrate 1 (IRS-1) is another key target of mTOR signaling that is associated with insulin resistance and an important regulator of insulin-stimulated glucose metabolism." (PMID 37830621, 2023). "JNK-mediated inhibition of insulin receptor substrate-1 (IRS-1) leads to insulin resistance and causes fatty liver." (PMID 37762367, 2023). "In particular, hsa-miR-3148 was reported to impair the insulin signaling pathway by downregulating IRS1, causing insulin resistance." (PMID 37762604, 2023). "An increase in the serine phosphorylation of IRS-1 at residues Ser307 and Ser636/639 is linked to impaired PI3K/Akt signaling and insulin resistance, and for this reason we first examined the effect of RA on IRS-1." (PMID 36982168, 2023). "One of the important causes of insulin resistance is the loss of the insulin signaling pathway in the liver, while the IRS-1/PI3K/Akt signaling pathway plays an important role in insulin signaling." (PMID 38201125, 2023). "The mechanisms started with PAKs or metabolic excess including TNF-α, endothelin-1, FFA or ER stress which exhibit ser/Thr phosphorylation of insulin receptor substrate 1(IRS1) and cause insulin resistance." (PMID 37014444, 2023). "It was reported that the mutation of IRS-1 serine phosphorylation sites protects mice against fat-induced insulin resistance." (PMID 35327570, 2022). "Insulin resistance is associated with a reduced ability of insulin to activate a variety of events in the insulin signaling system, such as tyrosine phosphorylation of IRS-1." (PMID 35320949, 2022). "They showed that during insulin resistance induced by ATM deficiency, JNK was activated, which consequently increased the level of inhibitory serine-307 phosphorylation on the insulin receptor substrate-1 (IRS-1) and caused insulin resistance." (PMID 35453338, 2022). "Insulin resistance has been shown to follow the phosphorylation of insulin receptor substrate 1 (IRS-1) by JNK activation linked to ER-stress." (PMID 35159342, 2022). "Polymorphisms in the IRS-1 gene in humans are associated with an increased risk of developing gestational diabetes, and the gene itself is involved in the development of insulin resistance in T2DM." (PMID 36248900, 2022). "Human G972R substitution (G965R on mouse IRS1) is the most common mutation of IRS1, which aggravates insulin resistance in obese patients." (PMID 35790738, 2022). "Increased serine phosphorylation of IRS-1 is linked to insulin resistance and for this reason, we examined IRS-1." (PMID 35011728, 2022). "In animal models of insulin resistance and type 2 diabetes, reduced glucose uptake was associated with decreased phosphorylation of IRS-1 tyrosine." (PMID 36005597, 2022). "Substitution of glycine to arginine at codon 972 (Gly972Arg) in the IRS1 gene carries a higher risk of insulin resistance." (PMID 36292779, 2022). "Insulin resistance is associated with reduced responses to insulin signaling in the IR/IRS-1/PI3K signaling pathway." (PMID 35563135, 2022). "IKKβ also causes insulin resistance by directly phosphorylating serine residues of insulin receptor substrate-1 (IRS-1)." (PMID 36145208, 2022). "Although post-translational modification of IRS-1 is crucial for the regulation of insulin sensitivity, a number of studies have found that low IRS-1 protein levels are closely associated with the development of insulin resistance and T2DM." (PMID 35328400, 2022).